BMI1 (BMI1 proto-oncogene, polycomb ring finger)
Diseases named in the same sentence as BMI1 in open-access papers (continued):
Sharing a sentence is not in itself a finding about the gene and the disease.
dysplasia (4 papers, 2012 to 2015). A usually neoplastic transformation of the cell, associated with altered architectural tissue patterns. "Predominance of ABCG2 positivity over Bmi-1 positivity was also observed for both dysplasia-derived cells (DOK and POE-9n) and two of the five OSCC-derived cells (PE/CA PJ15 and SCC25)." (PMID 24415717, 2014). "All five OSCC-derived cell lines exhibited greater proportions of Bmi-1-positive cells than the normal tissue and dysplasia-derived cells." (PMID 24415717, 2014). "As an attempt towards identifying the expression status of BMI1 in during progressive stages of CaP, we measured its levels by performing immunoblot analysis of human prostatic tissues from normal, dysplasia and CaP patients." (PMID 23671559, 2013). "The accumulation of high Bmi-1 expression from columnar cell metaplasia, Barrett’s esophagus, dysplasia to adenocarcinoma implies an important role of Bmi-1 in the early development of esophageal adenocarcinoma." (PMID 23078618, 2012). "The increase in high Bmi-1 expression was significant from squamous mucosa to columnar cell metaplasia and Barrett’s esophagus and from Barrett’s esophagus to low-grade dysplasia and esophageal adenocarcinoma." (PMID 23078618, 2012). "We previously found that cells with high BMI1 expression had different distribution patterns in different types of tissue: mostly within the bottom of metaplastic columnar cell tissue compared with the full-gland distribution in dysplasia and adenocarcinoma." (PMID 26156831, 2015). "High Bmi-1 expression significantly increased from squamous epithelium (7%), columnar cell metaplasia (22%), Barrett’s esophagus (22%), to low- (45%) and high-grade dysplasia (43%) and adenocarcinoma (37%)." (PMID 23078618, 2012). "Also, the distribution of cells with high Bmi-1 expression was observed to have a different pattern, mostly within the base of columnar cells metaplasia compared with the full gland distribution in dysplasia and adenocarcinoma." (PMID 23078618, 2012).
epithelial dysplasia (4 papers, 2007 to 2020). "Higher Ki-67 and BMI-1 expression was observed in lesions in the tongue and floor of the mouth, epithelial dysplasia, OSCC development and poor clinical evolution; however, the associations were not statistically significant." (PMID 32348447, 2020). "Enhanced-Bmi-1 expression was also detected in situ in the archived oral mucosal tissues with cancerous and precancerous histopathology, including that of mild epithelial dysplasia." (PMID 17179983, 2007). "Bmi-1 may also play a role in the progression of potentially malignant lesions as it has been observed that Bmi-1 overexpression occurs in mild, moderate, and severe epithelial dysplasia." (PMID 23533441, 2013). "Importantly, Bmi1 overexpression was observed in a majority (10/16) of the preneoplastic PanIN lesions with moderate to severe degrees of epithelial dysplasia." (PMID 23437065, 2013). "Importantly, Bmi-1 overexpression was also observed in 100% (9/9) of the preneoplastic oral mucosal tissues which included those with mild, moderate, or severe epithelial dysplasia." (PMID 17179983, 2007).
esophageal adenocarcinoma (4 papers, 2012 to 2017). A malignant tumor with glandular differentiation arising predominantly from Barrett mucosa in the lower third of the esophagus. "High CA9 expression was significantly associated with high BMI1 expression in esophageal adenocarcinoma and precancerous lesions." (PMID 26156831, 2015). "High expression of Bmi-1 was significantly associated with poor differentiation in esophageal adenocarcinoma (67%)." (PMID 23078618, 2012). "The expression level of Bmi-1 was significantly associated with esophageal adenocarcinoma differentiation." (PMID 23078618, 2012). "In addition, the expression level of Bmi-1 protein was significantly associated with worse histologic grade of esophageal adenocarcinoma." (PMID 23078618, 2012). "High expression of BMI1 has also been found in esophageal adenocarcinoma and esophageal squamous cell carcinoma." (PMID 26156831, 2015). "The expression of Bmi-1 in columnar cell metaplasia and Barrett’s esophagus also distributed at the base of glands, but the intensity and percentage of Bmi-1 was greatly increased." (PMID 23078618, 2012). "In esophageal adenocarcinoma, Bmi-1 amplification was detected by DNA microarray in a low percentage (3%)." (PMID 23078618, 2012). "This study demonstrates that high expression Bmi-1 is associated with esophageal adenocarcinoma and precancerous lesions, which implies that Bmi-1 plays an important role in early carcinogenesis in esophageal adenocarcinoma." (PMID 23078618, 2012). "In esophageal adenocarcinoma, the amplification of Bmi-1 was very low (3%) by DNA microarray study compared with to the high expression (37%) by immunohistochemical study." (PMID 23078618, 2012). "The frequency of high Bmi-1 expression in Barrett’s esophagus and columnar cell metaplasia was significantly greater than squamous epithelium (p < 0.05)." (PMID 23078618, 2012). "The analysis revealed a significant correlation between high expression of Bmi-1 in esophageal adenocarcinoma with moderately to poorly differentiated esophageal adenocarcinoma." (PMID 23078618, 2012). "High expression of Bmi-1 was significantly correlated with the histologic grade of esophageal adenocarcinoma." (PMID 23078618, 2012). "The esophageal adenocarcinoma and low- and high-grade dysplasia groups, also showed significantly greater frequency of high Bmi-1 expression compared with the Barrett’s esophagus and columnar cell metaplasia groups (p < 0.05)." (PMID 23078618, 2012). "In this study, we reported the first evidence that high expression of Bmi-1 occurred in esophageal adenocarcinoma and its precursor lesions including, low- and high-grade dysplasia, Barrett’s esophagus and columnar cell metaplasia." (PMID 23078618, 2012). "Finally, we analyzed the association of CA9 overexpression with BMI1, cyclin E, MCM4, MCM7 and Ki67 expression in esophageal adenocarcinoma." (PMID 26156831, 2015). "While our study showed high Bmi-1 expression of shows slightly better but not a significant difference in prognosis in esophageal adenocarcinoma, most studies showed that high Bmi-1 expression was associated with poorer prognosis." (PMID 23078618, 2012). "However, little is known about the role of Bmi-1 in esophageal adenocarcinoma." (PMID 23078618, 2012). "High Bmi-1 expression increased in intensity and percentage following the early progress of adenocarcinoma from squamous epithelium (7%), columnar cell metaplasia (22%), Barrett’s esophagus (22%), low- (45%) and high-grade dysplasia (43%) and adenocarcinoma (37%)." (PMID 23078618, 2012). "However, the percentage of high Bmi-1 expression increased following the histologic changes from squamous epithelium (7%) to columnar cell metaplasia (22%), Barrett’s esophagus (22%), low-grade dysplasia (45%), high-grade dysplasia (43%) and esophageal adenocarcinoma (37%)." (PMID 23078618, 2012).
esophageal adenocarcinoma (continued). "Bmi1 is a stem cell marker with similar distribution to those of MCM4, MCM7, and Ki-67 in esophageal adenocarcinoma and precancerous lesions." (PMID 27476776, 2016). "The non-significant prognosis for esophageal adenocarcinoma was unexpected since other gastrointestinal carcinomas showed worse prognosis with high Bmi-1 expression." (PMID 23078618, 2012). "For esophageal adenocarcinoma, the overall survival in the group with high Bmi-1 expression was 38.3 months, while the group with non-high Bmi-1 expression was 36.5 months." (PMID 23078618, 2012). "We assumed that high Bmi-1 expression may be involved at the transcriptional level without significant DNA amplification, suggesting that the higher expression in esophageal adenocarcinoma is not driven by changes in the DNA copy number." (PMID 23078618, 2012).
gallbladder cancer (4 papers, 2015 to 2021). "CCAT1 knockdown repressed the proliferation and invasion of gallbladder cancer cells via miR-218-5p controlling BMI1 transcript translation." (PMID 34321511, 2021). "For example, lncRNA CCAT1 could act as ceRNA of miRNA-218-5p to correlate with BMI1 mRNA levels in gallbladder cancer." (PMID 27966454, 2017). "Moreover, CCAT1 transcript levels were correlated with that of Bmi1 in gallbladder cancer tissues." (PMID 26040010, 2015).
gastric adenocarcinoma (4 papers, 2018 to 2022). "This study aimed to investigate whether and how Moloney murine leukemia virus integration site 1 (Bmi-1) plays a role in the regulation of glucose transporter 1 (GLUT1) in gastric adenocarcinoma (GAC)." (PMID 35415241, 2022). "In this study, we attempted to examine the Bmi-1 protein expression in primary gastric adenocarcinoma (GAC) tissues in comparison with noncancerous specimens among patients undergoing surgical resection and to assess its association with the SUVmax obtained by 18F-FDG PET/CT in GAC." (PMID 36561502, 2022).
myocardial infarction (4 papers, 2016 to 2023). Gross necrosis of the myocardium, as a result of interruption of the blood supply to the area, as in coronary thrombosis. "The follow-up study by this group showed that BMI1-derived cells give rise to CMs after myocardial infarction, establishing the observation that BMI1 expressing CPCs are the source of progenitors that aide in cardiac repair." (PMID 34680880, 2021). "Otherwise, myocardial infarction induced a significantly increase (2.7‐folds) of Bmi‐1 GFPhi population, mainly within the infarction and border zones." (PMID 30396232, 2019). "Our study provides evidence that Bmi1-derived cells contribute to de novo generation of CM after myocardial infarction, which is greater than for heart homeostasis with ageing." (PMID 27472922, 2016). "We have evaluated the role of cardiac Bmi1+ progenitor cells (Bmi1-CPC) following acute myocardial infarction (AMI)." (PMID 27472922, 2016). "Furthermore, in response to myocardial infarction, only the Bmi‐1 high‐expressing cells were increased about 2.7‐folds in the infarcted heart, mainly observed in the infarction and border zones, which suggests a potential role for myocardial repair after injury." (PMID 30396232, 2019). "Here we show that Bmi1-CPC have a stemness genetic profile, are activated, and contribute to de novo CM after acute myocardial infarction (AMI)." (PMID 27472922, 2016).
Oral leukoplakia (4 papers, 2014 to 2026). A thickened white patch on the oral mucosa that cannot be rubbed off. "For instance, oral leukoplakia and inflammatory hyperplasia specimens (premalignant lesions) displayed higher BMI1 expression compared with normal oral mucosa samples." (PMID 41385756, 2026). "A recent long-term follow-up study of 135 patients associated two stem cell markers, ATP-binding cassette G2 subfamily (ABCG2) and Bmi-1 with transformation of oral leukoplakia to cancer." (PMID 24415717, 2014).
renal fibrosis (4 papers, 2017 to 2024). A final common manifestation of a wide variety of chronic kidney diseases characterized by glomerulosclerosis and tubulointerstitial fibrosis. "This study explores whether Bmi1 deficiency leads to renal fibrosis through driving RTEC senescence/SASP, oxidative stress and DDR." (PMID 38617548, 2024). "In this section of our study, we aimed to explore whether Chk2 knockout could ameliorate aging-related renal fibrosis resulting from Bmi1 deficiency." (PMID 38617548, 2024). "Finally, we investigated whether Bmi1 deficiency leads to renal fibrosis by evaluating fibrotic changes in renal tissues." (PMID 38617548, 2024). "Recently, our studies demonstrated that B lymphoma Mo‐MLV insertion region 1 homologue (Bmi1), which is responsible for Twist‐induced EMT in cancer cells 58, is associated with hypoxia‐induced EMT in human tubular epithelial cells and renal fibrosis." (PMID 29314610, 2018). "Notably, the attenuation of EMT by Chk2 knockout implies that Bmi1 deficiency provokes EMT and renal fibrosis partly through DNA damage-induced cellular senescence." (PMID 38617548, 2024). "Our recent study in kidney diseases has demonstrated that 59 Bmi1 was involved in hypoxia‐triggered EMT in TECs and renal fibrosis, and the region of Bmi1 promoter not only contained the potential HIF‐1α‐binding site but also the Twist‐binding site." (PMID 28097825, 2017). "Similarly, hypoxia-induced Bmi1 can promote the manifestation of EMT and renal fibrosis through PI3K/AKT signaling pathway." (PMID 34869303, 2021).
skin cancer (4 papers, 2012 to 2022). "Overexpression of the Bmi-1 was found in high-grade B-cell non-Hodgkin Lymphomas (NHLs), colorectal cancers, ovarian cancer, breast, cervical, skin cancer, neuroblastoma, and nonsmall cell lung cancer (NSCLC)." (PMID 23984324, 2013). "It is interesting to speculate that some of the stem cell survival proteins we have localized in skin cancer stem cells, including Oct4, Sox2, Ezh2 and Bmi-1, may provide such targets." (PMID 24376802, 2013). "One possible explanation could be related to a role of UTF1 in cell division as it was proposed for the B lymphoma Mo-MLV insertion region 1 homolog (BMI-1) gene in skin cancer but the mechanism behind these observations is still unknown." (PMID 22880087, 2012).
thyroid cancer (4 papers, 2021 to 2023). "Nevertheless, our study provides evidence that activation of the Shh pathway plays an important role in regulating SOX2 and BMI1 expression in thyroid cancer." (PMID 33499351, 2021). "Our present study focused on the expression and regulation of SOX2 and BMI1 by the Shh pathway in thyroid cancer." (PMID 33499351, 2021). "The BMI1 inhibition function suggests that DSF/copper could be a combination drug for preventing the drug resistance of multitargeted kinase inhibitors in thyroid cancers." (PMID 36362068, 2022). "Whether BMI1 expression is dysregulated in thyroid cancer and has a role in thyroid CSC self-renewal remains to be investigated." (PMID 33499351, 2021). "Further studies are needed to evaluate the BMI1 gene expression in other thyroid cancers." (PMID 34551814, 2021). "The objective of our current investigation was to determine the role of the Shh pathway in regulating BMI1 and SOX2 expression in thyroid cancer and promoting thyroid tumor growth and development." (PMID 33499351, 2021). "GANT61 also inhibited BMI1 and SOX2 expression in WRO82 cells, a third thyroid cancer cell line with wild-type BRAF gene." (PMID 33499351, 2021). "Clinicopathological analyses of thyroid tumor specimens by immunohistochemical (IHC) staining revealed that BMI1 and SOX2 were highly expressed in thyroid cancer and correlated with Gli1 expression." (PMID 33499351, 2021). "Here we report that BMI1 and SOX2 were highly expressed in thyroid cancer and correlated with Gli1 levels." (PMID 33499351, 2021). "Our study provides evidence that activation of the Shh pathway leads to increased BMI1 and SOX2 expression in thyroid cancer and promotes thyroid CSC-driven tumor initiation." (PMID 33499351, 2021). "Our study grants new insights into the mechanisms of increased BMI1 and SOX2 expression in thyroid cancer and highlights the potential of the Shh pathway inhibitors as anticancer agents for preventing tumor recurrence." (PMID 33499351, 2021). "Finally, we conducted immunohistochemistry staining to detect the expression of BMI1 and SOX2 in thyroid cancer." (PMID 33499351, 2021). "Our study provides evidence that the Shh pathway regulates BMI1 and SOX2 expression and could be potentially targeted for anti-thyroid cancer therapy." (PMID 33499351, 2021). "The authors report that the Shh pathway regulates the expression of BMI1 and SOX2, two genes involved in stem cell self-renewal, and that targeting the Shh pathway has little effect on thyroid tumor xenografts but can inhibit the growth of tumor xenografts derived from thyroid cancer stem cells." (PMID 33499351, 2021). "Third, though it is well established that BMI1 and SOX2 play an important role in regulating stem cell self-renewal in a variety of malignancies, we did not further investigate if this is the case in thyroid cancer." (PMID 33499351, 2021).
ameloblastoma (3 papers, 2019 to 2021). The most common odontogenic tumor, arising from the epithelial component of the embryonic tooth and usually affecting the molar-ramus region of the mandible or maxilla. "The presence of patterns of five human PcG proteins (Bmi-1, Ring1b, Mel-18, Ezh2, and Suz12) in ameloblastomas and odontogenic keratocysts was previously analyzed." (PMID 33680332, 2021). "In our study we observed a widespread expression of the dental epithelial stem cell markers SOX2 and BMI1 within ameloblastoma." (PMID 32155948, 2020). "We then assessed the expression of the dental epithelial stem cell markers BMI1 and SOX2 in human ameloblastoma biopsies." (PMID 32155948, 2020). "As their expression is associated with that of the dental epithelial stem cell markers BMI1 and SOX2, it is reasonable to hypothesize that Notch ligands and receptors might contribute to the maintenance of stemness of ameloblastoma cells." (PMID 32155948, 2020). "In contrast, Bmi1 is confined to the core of the ameloblastoma nests and not highly expressed in the proliferative periphery of the structures." (PMID 31685919, 2019).
Ataxia (3 papers, 2014 to 2025). Ataxia refers to impaired coordination of voluntary muscle movement. "These mice did exhibit neurological deficits that worsened during aging, such as ataxia, as was reported in germline Bmi-1 deficient mice." (PMID 24843006, 2014). "In the Bmi-1-deficient mouse model, a significantly small size and an ataxia phenotype were observed, and these phenotypes could be restored by intercrossing the BMI-1-deficient mice with Ink4a/Arf locus-deficient mice." (PMID 32759846, 2020). "Bmi1 knockout mice weresmaller with lower body weight than WT littermates, and displayed ataxia, and impaired motor development." (PMID 41321489, 2025). "Bmi1 null mice are small with low body weight and manifest neurologic abnormalities such as ataxia, tremors, and seizures." (PMID 41321489, 2025).
bile duct tumor (3 papers, 2016 to 2025). "We have previously demonstrated that Bmi1 is upregulated in HCC with bile duct tumor thrombi, a subtype of HCC characterized by profuse expression of hepatic stem cell markers." (PMID 26926789, 2016).
bone cancer (3 papers, 2011 to 2024). A primary or metastatic malignant neoplasm affecting the bone or articular cartilage. "Overexpression of Bmi-1 in bone cancer cells promotes proliferation and angiogenesis and increases apoptosis resistance induced by cisplatin via the nuclear factor-kappa B (NF-kappa B) signal pathway." (PMID 30984268, 2019). "Statistical analysis indicated that positive expression of BMI-1 in benign and malignant bone tumors was significantly different, but elevated expression of BMI-1 was not correlated with any clinicopathologic parameters in the available 90 specimens." (PMID 21311599, 2011).
brain cancer (3 papers, 2020 to 2025). A primary or metastatic malignant neoplasm affecting the brain. "In summary, by characterizing the BMI1 interactome we have identified novel regulatory roles for this protein in GBM, which will facilitate further exploration of its druggability in this currently untreatable, aggressive form of brain cancer." (PMID 34316702, 2021).